IL6 (interleukin 6)
Diseases named in the same sentence as IL6 in open-access papers (continued):
Sharing a sentence is not in itself a finding about the gene and the disease.
metabolic disorders (continued). "This increase in IL-6 upon TEL treatment was unexpected, given that other investigators have demonstrated reduced IL-6 plasma levels in response to ARBs in cells and in humans or animals suffering from cardiovascular or metabolic diseases, thus suggesting anti-inflammatory effects under ARBs." (PMID 35431918, 2022). "Greater benefits of evening exercise in patients with metabolic disorders are hypothesized to be explained by the Nrf2-dependent activation of the antioxidant response element (ARE) region in skeletal muscles, binding to the promoter region of the interleukin 6 (IL-6) gene." (PMID 39941257, 2025). "However, no research has yet confirmed that IL-6 is the main factor in postpartum CVD and metabolic diseases in GDM patients." (PMID 39655348, 2024).
neurodegenerative disease (246 papers, 2009 to 2026). A disorder of the central nervous system characterized by gradual and progressive loss of neural tissue and neurologic function. "During the inflammatory process, HMGB1 is secreted from necrotic cells and binds to many receptors, which triggers the release of many cytokines that cause inflammation and the development of neurodegenerative diseases, including IL-6, TNFα, and IL-1β." (PMID 41351800, 2025). "In the context of neurotoxicity, IL6 has been implicated in the progression of neurodegenerative diseases, and it is able to influence neuronal survival and function." (PMID 40238193, 2025). "Abnormal increases in the levels of TNF‐α and IL‐6 trigger a neuroinflammatory response, which is associated with various neurodegenerative diseases." (PMID 40458084, 2025). "In recent years, interferon gamma, cytokines, risk factors, working memory, interleukin-6, older adults, and neurodegenerative diseases have emerged as the strongest citation burst keywords." (PMID 40791247, 2025). "Increased levels of IL-6 are linked to neurodegenerative diseases, and research studies reveal that PD patients’ blood and CSF have higher levels of IL-6." (PMID 40933823, 2025). "IL-6, a key proinflammatory cytokine, has been implicated in the pathogenesis of neurodegenerative diseases, such as MCI and AD." (PMID 40748886, 2025). "IL-6 has been associated with a spectrum of central nervous system disorders, including nerve damage, neurodegenerative diseases, etc.." (PMID 39407182, 2024). "Increasing levels of major proinflammatory cytokines, including TNF-α, IL-1β, and IL-6, are associated with several inflammatory-related neurodegenerative diseases." (PMID 37049819, 2023). "In essence, while acute exercise triggers a beneficial IL-6 response that protects the brain, chronic exercise lowers the baseline of IL-6, potentially reducing chronic inflammation and the risk of neurodegenerative diseases." (PMID 38137886, 2023). "Several studies have implicated IL-6 trans-signaling as the major contributor to chronic inflammation with age as well as in neurodegenerative disease models." (PMID 32669383, 2020). "On the other hand, estrogen deficiency is associated with the increase in proinflammatory cytokines, such as interleukin (IL)-1, IL-6, and tumor necrosis factor-α, which is linked to the development of AD or neurodegenerative disease." (PMID 31885921, 2019). "Activation of microglial cells results in the production of major proinflammatory cytokines, TNF-α and IL-6, during CNS inflammation, which is typically associated with neurodegenerative diseases including AD." (PMID 31057649, 2019). "These resident cells produce a plethora of cytokines such as interleukin 1β (IL-1β) and interleukin 6 (IL-6) which are implicated in several neurodegenerative diseases." (PMID 27681882, 2016). "Many studies demonstrated that some of the proinflammatory cytokines, such as TNF-α, IL-1β, and IL-6, play a key role in the development and maintenance of inflammation, and this cytokine elevation is associated with neurodegenerative diseases." (PMID 25157358, 2014). "Pro-inflammatory genes and cytokines such as TNFα, IL-1 and IL-6 are associated with human neurodegenerative diseases." (PMID 23675513, 2013). "CASP3, TNF, and IL6 are involved in processes such as apoptosis, oxidative stress, ROS formation, axonal transport defects, and age-related signaling pathways associated with diabetic complications in multiple neurodegenerative diseases." (PMID 41601963, 2026). "Pro-inflammatory factors such as TNF-α, IL-6, and IL-1β, released by activated microglia during neuroinflammation, are pivotal in initiating inflammatory responses, regulating cytokine cascades, and being implicated in neurodegenerative diseases." (PMID 39201475, 2024).
neurodegenerative disease (continued). "Serum levels of IL-6 should be monitored to see whether there is a correlation or a causative role between the increase in IL-6 levels and the development of neurodegenerative diseases." (PMID 38891863, 2024). "Cultured microglia initiate a robust proinflammatory response when exposed to LPS, an agonist of toll-like receptors, resulting in an altered gene signature and release of proinflammatory cytokines (e.g., IL1b, TNF, and IL6), which are implicated in neurodegenerative diseases." (PMID 35526014, 2022). "Based on the findings from existing literature, it has been suggested that high levels of IL-6 may increase the risk of developing neurodegenerative diseases." (PMID 35479493, 2022). "Activation of astrocytes and microglias result in the production of major proinflammatory cytokines (TNF-α, IL-6, or IL-1β) and neurotoxic factors (reactive oxidative species and tumor necrosis factor-α), which are typically associated with neurodegenerative diseases including AD." (PMID 32587516, 2020). "In contrast, in conditions where elevated IL-6 is well documented to be associated with neurodegenerative diseases, inhibiting IL-6 may be an approach to reduce and/or ameliorate IL-6 in the CNS." (PMID 32546183, 2020). "Moreover, chronic or excessive activation of glia by IL-6 is a common denominator in neuronal loss in several neurodegenerative diseases." (PMID 30260985, 2018). "Furthermore IL-6 was also secreted in response to FG and elevation of this cytokine has been implicated in a number of neurodegenerative diseases including AD." (PMID 30524237, 2018). "The expressions of IL-1β, IL-6 and iNOS are associated with neurodegenerative diseases." (PMID 28340576, 2017). "Microglia activated by LPS stimulation led to the production of proinflammatory cytokines and mediators, such as TNF-α, IL-6, and IL-1β, and their chronic increase predisposes the CNS to neuroinflammation, which may result in the development of neurodegenerative diseases, such as AD." (PMID 40720378, 2025). "Under conditions of neurodegenerative diseases, ROS activates the transcription factor NFκB in glial cells, causing it to transfer from the cytoplasm to the nucleus, thereby promoting the transcription of some important pro-inflammatory genes, including IL-1β, IL-6, and TNF-α." (PMID 40699625, 2025). "NMN has been shown to mitigate these effects by modulating oxidative stress markers (e.g., SOD, CAT) and inflammatory cytokines (e.g., TNF-α, IL-1β, IL-6), thus underscoring its potential in protecting against neurodegenerative diseases." (PMID 40276601, 2025). "Lowering the levels of TNF-α, IL-6, and IL-1β can prevent the development and progression of inflammatory and degenerative diseases." (PMID 41471283, 2025). "Taken together, these results raise important questions regarding the role of IL6 trans-signaling as a distinct process that contributes to accelerating disease pathologies in neurodegenerative diseases such as ALS." (PMID 39851451, 2025). "The plasma levels of pro-inflammatory cytokines (IL-6, TNF and IL-1β) are accepted as risk factors in cardiovascular and neurodegenerative diseases and increase in elderly with various comorbidities." (PMID 40149697, 2025). "This suggests that immune regulators such as interferon gamma and interleukin-6, among other cytokines, may serve as risk factors for cognitive function in the elderly population and are closely related to the onset and progression of neurodegenerative diseases." (PMID 40791247, 2025). "NF-κB activation by ROS contributes to neuroinflammation and neurodegenerative diseases.Upregulation of pro-inflammatory cytokines (IL-6) accelerates neuronal damage.Chronic NF-κB activation in glial cells exacerbates oxidative stress and neurotoxicity." (PMID 40214466, 2025).
neurodegenerative disease (continued). "This process helps to protect neurons from Aβ toxicity in AD, suggesting that the exercise-induced hormone irisin plays a crucial role in regulating the IL-6-mediated response in neurodegenerative diseases." (PMID 40843259, 2025). "These disturbances often coexist with elevated levels of inflammatory cytokines, particularly interleukin-6 (IL-6), which contribute to the development of cardiovascular and neurodegenerative diseases." (PMID 40710520, 2025). "A study has demonstrated that interleukin-6 drives the progression of neurodegenerative diseases by modulating acid-sensing ion channel 1a." (PMID 41230544, 2025). "Numerous studies have substantiated the involvement of IL-6 and IL-8 in the pathogenesis of neurodegenerative diseases, establishing their utility as clinical markers." (PMID 39201378, 2024). "The classical IL-6 signaling pathway profoundly influences neurodegenerative diseases, playing an essential role in various aspects of their pathophysiology." (PMID 39015561, 2024). "Understanding the IL-6/IL-6R axis is essential for developing targeted therapies for a variety of diseases, including autoimmune disorders, neurodegenerative diseases, and metabolic syndromes." (PMID 39015561, 2024). "Elevated IL-6 levels in the central nervous system worsen neuroinflammation in neurodegenerative diseases by activating microglia and astrocytes and releasing pro-inflammatory cytokines and neurotoxic molecules." (PMID 39015561, 2024). "Elevated levels of proinflammatory cytokines such as IFN‐γ, IL‐1β, IL‐6, IL‐18, and TNF‐α have been shown to induce tau hyperphosphorylation and neuronal loss in AD and other neurodegenerative diseases." (PMID 38923171, 2024). "Currently, it can be assumed that of the interleukins, IL-6 is the most extensively studied and described, also in relation to its significance for neurodegenerative diseases, including AD and MS." (PMID 39456713, 2024). "The role of IL-8 in the development of neurodegenerative diseases is less understood compared to IL-6." (PMID 39201378, 2024). "The fact that the prevention of complement activation in the current study also reduce downstream IL-6 activation, is therefore interesting from the perspective of multiple neurodegenerative diseases that have IL-6 elevations in common." (PMID 37704739, 2023). "Third, the activation of microglia and astrocytes induced by damage-associated molecular patterns (DAMPs) results in an increased release of the inflammatory cytokines TNF-α, IL-1β and IL-6 in cerebellum, which mediates neurodegenerative diseases." (PMID 37626842, 2023). "Under various neurodegenerative disease conditions, activated microglia release inflammatory cytokines and neurotoxic substances such as IL-1β, IL-6, TNF-α, and nitric oxide (NO), resulting in progressive neuronal degeneration in PD." (PMID 38138478, 2023). "Pro-inflammatory cytokines, such as TNF-α, IL-6 and IL-1β, play a crucial role in the pathophysiology of neurodegenerative diseases." (PMID 37521470, 2023). "After TBI, microglia was quickly activated and released various inflammatory mediators, including TNF-α, IL-1B, IL6, NO and ROS, which have been proved to be related in some neurodegenerative diseases." (PMID 36869312, 2023). "TNF-α and IL-6 have been found to be involved in the pathogenesis of neurodegenerative diseases, and TNF-α inhibitors are thought to have therapeutic potential in AD by improving cognitive performance." (PMID 37108458, 2023). "In neurodegenerative diseases, which are defined by neuronal degeneration and neuronal death in certain parts of the central nervous system (CNS), neuroinflammation by TNF-α and IL-6 is a crucial pathogenic mechanism underpinning neural death." (PMID 37871107, 2023). "The increasing expression of IL-6 was involved in the deterioration of cognitive functions during aging and neurodegenerative diseases." (PMID 36526934, 2023).
neurodegenerative disease (continued). "We performed RT-PCR to determine the changes in the mRNA expression of pro-inflammatory markers interleukin-1β (IL-1β), tumor necrosis factor-α (TNF-α), interleukin-6 (IL-6), and iNOS based on their potential involvement in neurodegenerative diseases." (PMID 37816735, 2023). "The growth of Streptococcus in the gut affects the levels of interleukin-6 and tumor necrosis factor-alpha and contributes to neurodegenerative diseases by inducing neuroinflammation." (PMID 38107849, 2023). "Proinflammatory cytokines, such as TNF-α and IL-6, play a crucial role in mediating the neuroinflammatory response and neurotoxicity in various neurodegenerative diseases." (PMID 37932682, 2023). "Evidence suggests that IL-6 contributes to neuroinflammation, thereby inducing neurodegenerative diseases." (PMID 37760893, 2023). "During neurodegenerative diseases, microglia are activated to mediate inflammatory responses, producing proinflammatory mediators (IL-6, TNF-α, iNOS, and COX2) and damaging neurons." (PMID 35418806, 2022). "Increasing the level of serum inflammatory cytokines such as interleukin-6 (IL-6) and tumor necrosis factor-α (TNF-α) in the elderly are considered risk factors for cardiovascular and degenerative diseases." (PMID 36160136, 2022). "In vitro studies showed that IL-6 promotes the survival and differentiation of neural cells, protecting against Ca2+ and ROS excitotoxicity Il-6 plays a role in neurodegenerative diseases such as AD." (PMID 33672427, 2021). "In particular, IL-1β, IL-6, and TNF-α are representative pro-inflammatory cytokines associated with various degenerative diseases." (PMID 34234892, 2021). "Several clinical studies indicated that IL-6 levels are elevated in the blood serum and cerebrospinal fluid (CSF) in patients with neurodegenerative disease or brain injury." (PMID 34832914, 2021). "IL-6 activates astrocytes and microglia, regulating the expression of neuropeptides after neuronal injury, for example, in neurodegenerative diseases." (PMID 34579104, 2021). "Researchers have found that patients with neurodegenerative disease display higher concentrations of IL-6,TNF-α, IL-1β, and NF-κB." (PMID 34944391, 2021). "IL6 is also reported to be a neurotoxic molecule wherein activated microglia can release IL6 and other neurotoxic molecules and affect PD and other neurodegenerative diseases." (PMID 34746302, 2021). "Research has shown that in the elderly, increased levels of serum inflammatory factors such as tumour necrosis factor-α (TNF-α), interleukin-6 (IL-6) and C-reactive protein (CRP) are considered to be risk factors of cardiovascular and degenerative diseases." (PMID 34925376, 2021). "On the other hand, high levels of pro-inflammatory cytokines (IL-6 and TNF) cause damage to the microglia promoting autoimmune and neurodegenerative diseases." (PMID 31694049, 2019). "IL‐6 is a well‐established proinflammatory cytokine that contributes to the pathogenesis of various degenerative diseases, and the role of IL‐6 as a key player in IDD has received attention recently." (PMID 30511395, 2019). "Due to neuroinflammation, an increase in the levels of endogenous IL-6 in the brain contributes to pathogenesis of some neurodegenerative diseases." (PMID 31297084, 2019). "TNF and IL-6 are two representative pro-inflammatory cytokines produced by microglia related to neurodegenerative diseases." (PMID 29807527, 2018). "Recent studies demonstrated that IL-1 and IL-6 are key players in neuroinflammation-induced astrogliosis, and astrogliosis is a characteristic feature of various neurodegenerative diseases." (PMID 29108257, 2017). "Pro-inflammatory cytokines, which include IL-1β, IL-6, and TNF-α, are believed to moderate neuroinflammation and cause cell death in different neurodegenerative diseases." (PMID 28490320, 2017).